CD44 (CD44 molecule (IN blood group))
Diseases named in the same sentence as CD44 in open-access papers (continued):
Sharing a sentence is not in itself a finding about the gene and the disease.
lymphoma (47 papers, 1993 to 2025). A malignant (clonal) proliferation of B- lymphocytes or T- lymphocytes which involves the lymph nodes, bone marrow and/or extranodal sites. "For example, overexpressed CD44 in lymphoma cells is associated with increased cell proliferation and survival." (PMID 36982699, 2023). "By studying the Ras-pathway-stimulated splicing of one these variant CD44 exons (exon v5), we discovered the RNA-binding protein Sam68 as a splice regulator directly modified by this pathway in mouse T-lymphoma cells." (PMID 18183298, 2008). "In addition to a strong expression of CD44s, variant isoforms of CD44 (CD44v) were observed predominantly in aggressive lymphoma." (PMID 23476138, 2013). "By applying a combination of various prediction algorithms, we identified the 3′-UTR of c-FOS as a potential target for miR-181a and miR-181b (down-regulated the in EBV-associated lymphomas), CD44 as a potential target of miR-20a and miR-106a, and the IL1R1 as a target of miR-205 and -125a." (PMID 22870299, 2012). "Expression of CD44 isoforms containing exon v10 is associated with metastasis in lymph nodes, resistance to radiotherapy and shorter disease-free survival in HNSCCs, as well as in other malignancies of hematopoietic origin, such as cutaneous leukemias and lymphomas." (PMID 33003440, 2020). "Using flow cytometry, we further evaluated CD44 surface levels on a small panel of DLBCL lymphoma cell lines of GCB (SUDHL6, OCI-Ly18, and OCI-Ly7) and ABC (U2932, TMD8, and HBL1) origin." (PMID 36982699, 2023). "Many previous studies reported an important functional role of CD44 in various types of cancer and increased CD44 expression has also been observed in lymphoma." (PMID 36982699, 2023). "Amongst DN lymphomas, it was most common to see lymphomas with a phenotype consistent with the DN4 stage of development (CD44- CD25-)." (PMID 37160922, 2023). "No study has previously reported the increased expression of Ig heavy chain V region GOM associated with canine lymphoma in the same way as with TIMP-1, APOH, and CD44." (PMID 35765478, 2022). "In our mouse model, CD44 was co-expressed only by a few CD20-positive lymphoma cells in the choroid and retina of the PCNSL group." (PMID 36233057, 2022). "The aberrant CD21 expression was significantly more frequent in TZL than in T-NOS lymphomas (p < 0.001), whereas the loss of CD5 and CD44 was more frequent in the latter (p < 0.001 and p = 0.004, respectively)." (PMID 35448684, 2022). "When compared with the lymphoma group, the proportion of CD44+ cells and the expression of TGF-β in the CTLA-4 inhibition group decreased significantly." (PMID 34553071, 2021). "Numerous studies indicated that lymphoma, breast, colon and endometrial cancer have elevated levels of CD44 mRNA." (PMID 34944493, 2021). "Correlation analysis showed that CTLA-4 expression positively correlated with CD44+ cell in lymphoma tissue and regulatory T (Treg) cells in lymphocytes." (PMID 34553071, 2021). "Previously, we reported that when cocultured with epithelial-like feeder cells, lymphoma cells form anchorage-dependent multicellular aggregates (Ad-MCAs) and that a fraction of aggregate-forming lymphoma cells acquire quiescent CD44-high CSC-like phenotypes." (PMID 30042817, 2018). "Another lymphoma dataset (Compagno Lymphoma Statistics) indicated that the expression levels of CD44 and STAT3 were higher in ABC than those in GCB." (PMID 29992138, 2018). "We show here, that CD44 expression is epigenetically regulated in lymphoma cell lines and presumably also in primary lymphoma." (PMID 20920234, 2010). "In the future, CD44 should be evaluated as a potential target for epigenetic therapy and as a target for antibody-based therapies in CD44+ lymphoma subtypes." (PMID 20920234, 2010). "CD44 hypermethylated, CD44- lymphoma cell lines were consistently resistant towards anti-CD44 induced apoptosis." (PMID 20920234, 2010).
lymphoma (continued). "The CD44 expression profiles obtained from lymphoma cell lines resemble previous reports on differential CD44 expression in diverse primary lymphoma entities." (PMID 20920234, 2010). "This supports a tumor suppressor role for CD44 in lymphoma and highlights CD44 as an interesting new potential epigenetic marker and a valuable target for epigenetic therapy in distinct lymphoma subtypes." (PMID 20920234, 2010). "Since only a small proportion of endogenous CD44 pre-mRNA molecules include CD44 exon v5 upon phorbol-ester stimulation in our lymphoma cell model, changes in protein binding to this minority of molecules would be difficult to detect." (PMID 18183298, 2008). "Furthermore, APN KO BMSCs were highly migratory toward EL-4 lymphoma, and the interaction between CD44 in BMSCs and hyaluronic acid (HA) from EL-4 enhanced the migration of BMSCs." (PMID 37370133, 2023). "Some studies have suggested that CD44 may play a role in the development and progression of lymphoma." (PMID 36982699, 2023). "Analyzing the publicly available dataset GSE94669, we could also notice that even though CD44 is a known marker for ABC DLBCL classification, CD44 levels are consistently higher in lymphoma cell lines expressing mutated MyD88." (PMID 36982699, 2023). "Additionally, targeting CD44 with specific drugs has been shown to inhibit the growth and proliferation of lymphoma cells in culture and animal models." (PMID 36982699, 2023). "The flow cytometry analysis of cells inducibly expressing MyD88L265P for 24 h revealed increased surface CD44 levels in U2932 lymphoma cells as well as other cell types, such as THP1 and U2OS, which could be reverted with 5Z7O treatment." (PMID 36982699, 2023). "We hypothesized that CXCR4, CXCR5, CXCR7 and CD44 are expressed on CD20-positive lymphoma cells in the eyes of this PCNSL PDX model." (PMID 36233057, 2022). "In our study, the 15% proportion of CD20/CXCR4-positive cells in all CD20-positive lymphoma cells may have negatively impacted the expression of CD44 on lymphoma cells." (PMID 36233057, 2022). "When considering TZL and T-NOS lymphomas, a significantly different prevalence of specific phenotypic aberrancies was found: aberrant CD21 expression was more common in TZL, whereas loss of CD5 and CD44 were more common in T-NOS." (PMID 35448684, 2022). "In PCNSL, lymphoma cells, which were often found perivascular, were CD44-positive." (PMID 36233057, 2022). "We show that expression levels of the two HA receptors, RHAMM and CD44, in diagnostic FL tumor-tissue samples from patients with and without subsequent transformation to a high-grade lymphoma can predict HT." (PMID 35267625, 2022). "Correlation analysis results showed that CTLA-4 expression was positively correlated with the proportion of CD44+ cells in lymphoma, indicating that CTLA-4 may have a certain correlation with tumor stem cells." (PMID 34553071, 2021). "CTLA-4 significantly increased the proportion of CD44+ CD34+ cells in lymphoma cells, and TGF-β neutralization could significantly block this effect of CTLA-4." (PMID 34553071, 2021). "Additionally, co-culture of RL cells in the presence of neutrophils and vincristine up-regulated the expression of CD44 by the lymphoma cells." (PMID 29069828, 2017). "However, more recently, a significant differential expression of CD44 between Burkitt lymphoma and CD10 DLBCL has been documented, making CD44 an excellent candidate for rapid immunophenotypic discrimination between these two types of lymphoma." (PMID 27567676, 2016). "Some experimental studies support a tumor suppressor function of CD44 in lymphomas; silencing of CD44 expression may facilitate lymphoma genesis." (PMID 25159097, 2014). "Lymph nodes involved by lymphoma also stained positive for CD44." (PMID 25159097, 2014).
lymphoma (continued). "Additonally, the interaction between CD44 expression by lymphoma cells and PCa cells remains unclear; further investigation is needed to assign a definite role to this transmembrane protein." (PMID 25159097, 2014). "According to these authors, such protection could result from the over-expression of circulating transmembrane molecule CD44 in leukemia and lymphoma patients." (PMID 25159097, 2014). "These experiments support the tumor suppressor function of CD44 in lymphoma." (PMID 20920234, 2010). "Furthermore, ligation of cell surface CD44 with an anti-CD44 antibody triggered apoptosis in CD44+ lymphoma cell lines, whereas CD44- cell lines with CD44 hypermethylation were resistant towards anti-CD44 induced apoptosis." (PMID 20920234, 2010). "Interestingly, CD44-positive cells were found in capillaries near CD20-positive lymphoma cells." (PMID 36233057, 2022). "Thus CD44 may be a promising new epigenetic marker for diagnosis and a potential therapeutic target for the treatment of specific lymphoma subtypes." (PMID 20920234, 2010). "Lymphomas lacking or with very weak homing receptor expression (n = 14, 52%) were associated with 57% 10-year survival rate as compared with only 15% among lymphomas that expressed CD44 more strongly (P = 0.02)." (PMID 8347502, 1993). "Lymphocyte homing receptor (CD44) is involved in lymphocyte adhesion to endothelial cells of high endothelial venules (HEVs) and lymphocyte exit from the blood circulation, and it may be involved also in hematogenous dissemination of malignant lymphoma." (PMID 8347502, 1993). "Thus, CD44 positive lymphoma cells might migrate towards a HA gradient of the brain and eye." (PMID 36233057, 2022). "In this study, we were able to show that CD20-positive lymphoma cells in a PCNSL PDX homing mouse model with a PVRL phenotype co-express the chemokine receptors CXCR4, CXCR5 as well as CD44 in comparison to a SCNSL PDX mouse model." (PMID 36233057, 2022). "Potential novel candidate biomarkers in canine lymphoma were ACTB, β2M, TIMP-1, CD44 antigen, Ig heavy chain V region GOM, APOC1, and APOH." (PMID 35765478, 2022). "A recent study by the group of Clemens Schmitt showed that the chemotherapeutic Adriamycin (Doxorubicin) induced senescence in mouse lymphoma cells and that these senescent lymphoma cells expressed stem cell markers such as CD133 or CD44." (PMID 35844581, 2022). "The first reported serum proteins in canine lymphoma were ACTB, Ig heavy chain V region GOM, TIMP-1, APOH, CD44, APOC1, and β2M." (PMID 35765478, 2022). "At the immunohistochemical level, it has been found that CD38 and CD44 can be used to distinguish between MYC-positive and MYC-negative lymphomas." (PMID 31484540, 2019). "The distinctive mBL signature consisted of 58 genes, including several target genes of the NF-κB pathway (i.e., BCL2A1, FLIP, CD44, NFKBIA, BCL3, and STAT3) that are known to distinguish activated B-cell-like or germinal center B-cell-like lymphomas." (PMID 26416427, 2015). "Our studies on TSG methylation patterns in lymphoma cell lines and patient samples led to the identification of novel epigenetically silenced TSG, with CD44 being the most interesting one." (PMID 20920234, 2010). "To test the functional relevance of this intronic Sam68 binding-element, we introduced the A/C mutation into a luciferase-based splice-reporter minigene carrying CD44 exon v5 and transfected it into LB17 mouse lymphoma cells." (PMID 18183298, 2008). "Additionally, monoclonal antibodies targeting CD44, CD47, and CD123 have shown efficacy against lymphoma in xenograft models." (PMID 41469420, 2025). "ACTB, aaaaaaaa2M, APOH, TIMP-1, CD44 antigen, Ig heavy chain V region GOM, and APOC1 are novel candidate proteins and might serve as a lymphoma biomarker in dogs." (PMID 35765478, 2022). "CD44 has not yet been examined in PVRL but is expressed by lymphoma cells and vascular endothelium in PCNSL and PTL." (PMID 36233057, 2022).
lymphoma (continued). "We compared the eyes of a lymphoma PDX model derived from a PCNSL versus SCNSL patient stereotactic CNS biopsy regarding infiltration of human CD20 positive lymphoma cells and immunohistochemical expression of the homing receptors CXCR4, CXCR5, CXCR7 and CD44." (PMID 36233057, 2022). "CD44 remains an interesting candidate receptor for PCNSL and thus also for PVRL, which may well contribute to homing of lymphoma cells into the eye." (PMID 36233057, 2022). "Introduction of EBV latent membrane protein I (LMP1) gene into BL cells induces expression of CD44 on the cell surface suggesting that expression of LMP1 may regulate expression of CD44 and play a role in the behavior of EBV-based lymphomas." (PMID 26527314, 2015). "Thus, higher CD74 and CD44 expressions mark CD27+ memory B cells compared with CD27- naïve B cells and differ from those of malignant lymphoma B cells overexpressing CD74." (PMID 22404985, 2012). "CD44 is one of two well-characterized receptors for hyaluronic acid (HA), and we have recently reported effective sensitization of human KSHV-infected lymphoma cells to chemotherapy using various approaches for interfering with HA-receptor interactions." (PMID 22505930, 2012). "Concordant results were obtained from primary lymphoma material: CD44 was not methylated in MCL patients (0/11) whereas CD44 was frequently hypermethylated in BL patients (18/29)." (PMID 20920234, 2010). "Our data show that CD44 is epigenetically regulated in lymphoma and undergoes de novo methylation in distinct lymphoma subtypes like BL." (PMID 20920234, 2010). "Six candidate increased proteins in canine lymphomas were beta-actin cytoplasmic 1 (ACTB, p=0.04), haptoglobin (p=0.002), beta-2 microglobulin (aaaaaaaa2M, p=0.007), beta-2 glycoprotein 1 (APOH, p=0.03), metalloproteinase inhibitor 1 (TIMP-1, p=0.03), and CD44 antigen (p=0.02)." (PMID 35765478, 2022). "Differently higher serum proteins in canine lymphoma were observed in beta-actin cytoplasmic 1 (ACTB, p=0.04), Hp (p=0.002), beta-2 microglobulin (β2M, p=0.007), beta-2 glycoprotein 1 (APOH, p=0.03), metalloproteinase inhibitor 1 (TIMP-1, p=0.03), and CD44 antigen (p=0.02)." (PMID 35765478, 2022). "No regulatory mechanisms for CD44 expression in lymphoma have been described so far." (PMID 20920234, 2010). "Immunohistochemistry staining with human CD44 and CD133 antibody showed that all cases were negative, which suggested that the identified lymphomas were not derived from gastric and colorectal tumor cells." (PMID 25819560, 2015). "We corroborated the gene expression data by monitoring the expression of several activation markers, including CD25, CD40L, HLA-DR, CD28, CD38, CD44 and CD69, showing no significant modulation when CAR.CD19-T cells are stimulated by the lymphoma DAUDI cells in the presence of INFγ neutralization." (PMID 37296093, 2023).
neuroblastoma (46 papers, 1997 to 2025). Neuroblastoma (NB) is the most common solid, extracranial childhood tumor. "CD44 encodes a cell-surface glycoprotein and affects the cell-cell interactions, cell adhesion, and migration, leading to a low survival in high-grade neuroblastoma, as well as synaptic remodeling and epileptogenesis." (PMID 33123575, 2020). "Consistently, the stemness-associated CD44+ population was significantly increased (p = 0.0165) in the siBRCA1-treated neuroblastoma cells." (PMID 31273285, 2019). "Endothelial CD44 variants V4, V5 and V7 have been shown to be modulated after endothelial contact with neuroblastoma cells, altering PMN adhesion to endothelium." (PMID 26943029, 2016). "CD44-expressing CSCs are associated with tumor aggressiveness and poor survival in neuroblastoma." (PMID 39518076, 2024). "Expression of CD44 was high in cells in which we overexpressed MOXD1, which is consistent with the previous finding that CD44 is expressed in undifferentiated multipotent neural crest cells and has been shown to be associated with favorable prognosis in neuroblastoma." (PMID 38905335, 2024). "Moreover, CD44 overexpression in NPCs enhanced both filopodia numbers and extensions, which are often associated with increased cell motility as previously observed for neuroblastoma cells and astrocytes." (PMID 23468987, 2013). "Of note, CD44 expression at transcription level correlates with mesenchymal tumor cell identity in neuroblastoma cell lines." (PMID 37142597, 2023). "Several of the identified miRNAs are acting over CD44 expression, which is a marker for neuroblastoma undifferentiated cells, and is also present in glial derivatives." (PMID 36675105, 2023). "CD44 is a proteoglycan whose expression levels are altered in various tumors as well as in childhood malignant neuroblastoma and in rhabdomyosarcoma." (PMID 35128576, 2022). "In neuroblastoma cells CD44 overexpression induced longer filopodia-like structures, which was associated with increased cell invasion." (PMID 32679746, 2020). "In the current study we evaluated L-, P- and E-selectin binding to neuroblastoma cells and the expression of some of their known ligands, namely CD44, CD24 and P-selectin glycoprotein ligand-1 (PSGL-1)." (PMID 29156825, 2017). "CD-44-negative, neuroblastoma-derived SK-N-DZ cells engineered to express CD-44 show that the interaction between HA and CD44 was partially responsible for the adenoviral-mediated enhancement effect." (PMID 28684419, 2017). "In contrast, the expression of CD44 was higher in ganglioneuromas and ganglioneuroblastomas when compared to neuroblastomas and only in one neuroblastoma patient CD44 was high with all probes." (PMID 29156825, 2017). "Observation of neuroblastoma cells revealed that these CD44 clusters localized to filopodia and focal bleb-like protrusions in neuroblastoma cells that enabled migration and invasive growth into brain tissue." (PMID 26029216, 2015). "Shtivelman and Bishop (1991) have shown that several upstream cis-acting elements contribute to the downregulation of CD44 gene expression in neuroblastoma cells." (PMID 25999819, 2015). "Structural analysis of the CD44 upstream regulatory region in human neuroblastoma cells revealed that there is a cis-regulatory element that contributes to downregulation of the CD44 gene." (PMID 12439723, 2002). "While CD44 has been documented to express low levels in normal adult neurons, astrocytes, and microglia, this receptor may be overexpressed by neuroblastoma and neuroglioma." (PMID 38931956, 2024). "Additionally, studies have shown that CD44-expressing neuroblastoma cells exhibit higher tumorigenic potential and are involved in maintaining the stemness of tumor cells." (PMID 39518076, 2024).